PCSK9 (proprotein convertase subtilisin/kexin type 9)
Diseases named in the same sentence as PCSK9 in open-access papers (continued):
Sharing a sentence is not in itself a finding about the gene and the disease.
steatosis (23 papers, 2017 to 2026). Increased lipid within the cytoplasm of cells. "In subgroup analysis, comparing patients with mild steatosis to patients with moderate to severe steatosis, AG + GG genotypes of PCSK9 rs505151 were associated with moderate and high grade steatosis in liver transplant recipients." (PMID 34876018, 2021). "In multivariate regression model, AG + GG genotypes of PCSK9 rs505151 were associated with moderate and severe steatosis in liver transplant recipients (OR 5.747; 95% CI 1.086–30.303; P value = 0.040)." (PMID 34876018, 2021). "In the liver, CD36 was highlighted as a strong contributor to steatosis and hepatic injury in the context of proprotein convertase subtilisin/kexin type 9 (PCSK9) deficiency." (PMID 34092215, 2021). "Significantly, the association between steatosis and PCSK9 level was uninfluenced by necroinflammation and hepatocellular ballooning." (PMID 31510106, 2019). "It has been reported that circulating PCSK9 levels increase with the severity of hepatic fat accumulation in patients at risk of NASH and PCSK9 mRNA levels in liver have been linked with steatosis severity." (PMID 28827398, 2017). "Hepatic PCSK9 protein expression decreases significantly with increasing steatosis severity, while circulating PCSK9 levels positively correlate with the degree of hepatic fat accumulation." (PMID 40764605, 2025). "The role of PCSK9 in promoting steatosis, a condition characterized by the buildup of fat in the liver, is widely supported by preclinical evidence." (PMID 38185721, 2024). "In this study, olanzapine induced an upregulation of hepatic LXRα and PCSK9 expression, accompanied by fat accumulation and steatosis in vivo and in vitro." (PMID 35379885, 2022). "Of note, metformin ameliorated the olanzapine-induced upregulation of LXRα and PCSK9, thus contributing to the reduction of hepatic fat accumulation and steatosis in vivo and in vitro." (PMID 35379885, 2022). "In this study, we demonstrated that metformin inhibits hepatic PCSK9 expression, in parallel to improving olanzapine-induced hepatic/hepatocyte steatosis in vivo and in vitro." (PMID 35379885, 2022). "Conversely, overexpression of PCSK9 in vitro dramatically attenuated the effects of metformin on hepatocyte steatosis." (PMID 35379885, 2022). "Our current findings indicated that olanzapine upregulated the expression of hepatic PCSK9 accompanied by hepatic/hepatocyte steatosis in vivo and in vitro, which is characterized by the increased size and number of lipid droplets within hepatocytes." (PMID 35379885, 2022). "Taken together, these results suggested that intact PCSK9 expression was required for olanzapine-induced steatosis, and the beneficial effect of metformin on olanzapine-induced lipid accumulation was dependent on PCSK9." (PMID 35379885, 2022). "In contrast, LXRα antagonist treatment profoundly suppressed PCSK9 expression, effectively reversing olanzapine-induced fat accumulation and steatosis in vitro." (PMID 35379885, 2022). "In support of this notion, a recent study found that hepatic expression of PCSK9 increases with severity of steatosis." (PMID 35323658, 2022). "In contrast, Ruscica and colleagues demonstrated that hepatic PCSK9 expression and circulating PCSK9 levels correlate with steatosis in morbidly obese patients who have undergone bariatric surgery." (PMID 35323658, 2022). "Hepatic PCSK9 mRNA expression was modestly increased with higher steatosis grade in patients with NAFLD." (PMID 35162992, 2022). "Serum PCSK9 was nevertheless positively correlated with steatosis grade, necroinflammation, hepatocyte ballooning, and fibrosis stage in the second cohort of patients with NAFLD." (PMID 33920491, 2021).
steatosis (continued). "Recently, a study on rat models with alcohol-induced steatosis showed that the treatment with alirocumab, a human PCSK9 monoclonal antibody, attenuated expression of FAS and alleviated alcohol-induced lipid accumulation." (PMID 33488522, 2020). "A recent study reported that steatosis induced by high fat diet in mice increased hepatic and plasma PCSK9 expression, thus diminishing LDL-R expression and elevating plasma LDL-C58." (PMID 31748600, 2019). "RSV attenuates steatosis and proprotein convertase subtilisin/kexin type 9 (PCSK9) expression through down-regulation of sterol regulatory element-binding protein 1 (SREBP-1c) expression, at least in part through ERα-mediated pathway in L02cells." (PMID 31546715, 2019). "Circulating PCSK9 has also been found to be significantly associated with hepatic expression of SREBP‐1c and FASN, whereas PCSK9 mRNA levels have been found to be significantly correlated with steatosis severity and hepatic APOB, SREBP‐1c, and FASN expression." (PMID 28827398, 2017). "This shows that inhibitors PCSK9 could be useful in liver diseases such as steatosis." (PMID 35323699, 2022). "Conversely, metformin administration attenuated the olanzapine-induced upregulation of PCSK9, FAS, and SCD1 as well as downregulation of SCAD and PPARα, effectively improving hepatic/hepatocyte steatosis." (PMID 35379885, 2022). "Our data suggest that FAF2 may regulate liver PCSK9 levels, potentially through the FOXO3-SIRT6 pathway, thereby contributing to the amelioration of ethanol-induced steatosis and the reduction in circulating LDL cholesterol." (PMID 39969435, 2025). "Elevated PCSK9 levels correlate with MASLD severity, hepatic inflammation, and steatosis." (PMID 41404533, 2025). "PCSK9 protein levels in hepatocytes did not correlate with the degree of steatosis or fibrosis in the entire cohort (p > 0.05 for both)." (PMID 41233786, 2025). "To date, no established connection exists between FAF2 and PCSK9 in the regulation of steatosis in ALD." (PMID 39969435, 2025). "However, hepatocyte PCSK9 and SREBP-2 protein expression was not correlated with the stage of steatosis and fibrosis in severe illness." (PMID 41233786, 2025).
colon cancer (22 papers, 2017 to 2025). "used colon cancer tissues to analyze the association between proprotein convertase subtilisin/kexin type 9 (PCSK9) expression and clinicopathological factors of patients." (PMID 41041328, 2025). "Colon cancer tissues were utilized for analysis of PCSK9 expression for association with clinicopathological factors from patients by immunohistochemistry assay." (PMID 36242053, 2022). "We revealed that PCSK9 protein was highly expressed in colon cancer tissues and associated with advanced tumor pathological grade." (PMID 36242053, 2022). "PCSK9 expression was upregulated in colon cancer tissues versus the normal tissues, and associated with advanced tumor pathological grade." (PMID 36242053, 2022). "This study assessed PCSK9 expression and functions in human colon cancer and then explored the underlying molecular events." (PMID 36242053, 2022). "Our current study showed that PCSK9 expression was upregulated in colon cancer tissues and associated with advanced tumor pathological grade, while the reduction of PCSK9 expression affected colon cancer cell proliferation, migration, and invasion in vitro." (PMID 36242053, 2022). "In colon cancer cells, the knockdown of proprotein convertase subtilisin/kexin type 9 (PCSK9) reduces both macrophage migration inhibitory factor (MIF) expression and lactylation levels, thereby promoting macrophage M1-type polarization." (PMID 40421024, 2025). "Proprotein convertase subtilisin/kexin type 9 (PCSK9) enhances colon cancer progression by modulating epithelial-mesenchymal transition (EMT) and PI3K/AKT signaling while skewing macrophage polarization." (PMID 40703527, 2025). "Other studies have indicated that the expression of proprotein convertase subtilisin/kexin type 9 (PCSK9) is upregulated in colon cancer tissues." (PMID 40443721, 2025). "In colon cancer cell lines, PCSK9 was shown to promote cell progression and metastasis by downregulating E-cadherin expression, inducing the colon cancer cell epithelial–mesenchymal transition process and activating PI3K/AKT signaling." (PMID 38611089, 2024). "Their previous experimental studies demonstrated that L-IFPTA + vaccine-mediated inhibition of PCSK9 moderately suppresses tumor growth and improves lifespan and survival in mice with breast and colon cancers." (PMID 39736777, 2024). "PCSK9 plays a crucial role in the progression and metastasis of colon cancer by regulating tumor cell EMT and the PI3K/AKT signaling pathway, and by mediating MIF and lactate levels to control macrophage phenotype polarization." (PMID 38714539, 2024). "To date, several studies have confirmed that the inhibition of PCSK9 attenuates the progression of breast cancer, glioma, colon tumors, and prostate cancer." (PMID 39736777, 2024). "PCSK9 expression was described as being upregulated in colon cancer tissue versus corresponding adjacent normal tissue, and associated with tumors of a pathological grade." (PMID 38611089, 2024). "In an experimental mouse models of breast and colon cancer, anti-PCSK9 vaccine, which led to lower plasma level and activity of PCSK9, was associated with moderate but not significant tumor growth reduction and prolongation of lifespan." (PMID 38672532, 2024). "He indicated that the knockdown of PCSK9 expression reduced colon cancer proliferation and metastasis by upregulation of Snail1 and, by this, downregulated E-cadherin expression while overexpressing N-cadherin." (PMID 38398019, 2024). "In another study in colorectal cancel model, authors founded that PCSK9 induces oncogenesis in APC/KRAS mutant models of colon cancer and that systemic PCSK9 levels correlate with reduced survival in this patient cohort." (PMID 36900189, 2023). "A study on colon cancer reveals that PCSK9 expression is upregulated in tumor cells compared with non-tumor cells and correlates with the degree of tumor invasiveness." (PMID 36900189, 2023).
colon cancer (continued). "In contrast, overexpression of PCSK9 significantly increased MIF protein levels in colon cancer cells." (PMID 36242053, 2022). "Knockdown of PCSK9 expression reduced colon cancer cell proliferation, migration, and invasion and suppressed tumor metastasis in vivo." (PMID 36242053, 2022). "A future study will investigate PCSK9 inhibition as a potential therapeutic approach to control colon cancer clinically." (PMID 36242053, 2022). "Our study demonstrated that PCSK9 promotes the progression and metastasis of colon cancer cells through multiple pathways." (PMID 36242053, 2022). "In contrast, levels of lactate, protein lactylation and MIF protein were significantly enhanced in colon cancer cells after PCSK9 overexpression." (PMID 36242053, 2022). "In summary, our current study comprehensively assessed the role of PCSK9 in progression and metastasis of colon cancer by analysis of colon cancer tissue samples, in vitro cell experiments, and in vivo animal experiments." (PMID 36242053, 2022). "To better understand the effects of PCSK9 knockdown in colon cancer cells, we analyzed the levels of the EMT process-related proteins." (PMID 36242053, 2022). "We then assessed changes in tumor cell proliferation, migration and invasion and found that PCSK9 overexpression did have the opposite effects on colon cancer cells in vitro." (PMID 36242053, 2022). "PCSK9 played an important role in the progression and metastasis of colon cancer by regulation of tumor cell EMT and PI3K/AKT signaling and in the phenotypic polarization of macrophages by mediating MIF and lactate levels." (PMID 36242053, 2022). "We then assessed the in vitro effects of PCSK9 knockdown on the regulation of colon cancer cell phenotypes." (PMID 36242053, 2022). "We also found that levels of lactate and protein lactylation was reduced in colon cancer cells after the reduction of PCSK9 expression." (PMID 36242053, 2022). "Manipulation of PCSK9 expression was assessed in vitro and in vivo for colon cancer cell proliferation, migration, and invasion using cell viability CCK-8, Transwell tumor cell migration and invasion, and wound-healing assays." (PMID 36242053, 2022). "To further confirm the oncogenic effects of PCSK9 expression in colon cancer cells, we over-expressed PCSK9 in HCT116 and HT-29 cells transiently." (PMID 36242053, 2022). "Again, this is the first report of a clear link of PCSK9 up-regulation in colon cancer, while NR1H4 down-regulation has been reported to result from promoter methylation with this cancer." (PMID 28962550, 2017). "Studies have shown that the progression of colon cancer is related to the epithelial mesenchymal transformation of tumor cells regulated by PCSK9 and PI3K/AKT signaling, which regulates the level of histone lactylation, playing a role in phenotypic polarization of macrophages." (PMID 41041328, 2025). "Focusing on the modulation of PCSK9 expression or its functional activity could be a potential therapeutic strategy for controlling colon cancer." (PMID 39876839, 2025). "Similarly, PCSK9 has been demonstrated to augment the proliferation, migration, and invasion of colon cancer cells in vitro by inducing EMT and activating the PI3K/AKT signaling pathway." (PMID 38706897, 2024). "Another study is related to PCSK9, which promotes metastasis in colon cancer via EMT regulation." (PMID 38398019, 2024). "Moreover, PCSK9 expression enhanced colon cancer cell proliferation, migration, and invasion in vitro by induction of tumor cell EMT and activation of the PI3K/AKT signaling." (PMID 36242053, 2022). "Besides, the concentration of lactate in the culture supernatant of HCT116 cells was significantly reduced after PCSK9 knockdown and thus we can deduce that PCSK9 promotes the level of lactate and protein lactylation in colon cancer cells." (PMID 36242053, 2022). "Collectively, our current data demonstrated the oncogenic activity of PCSK9 in colon cancer." (PMID 36242053, 2022).
colon cancer (continued). "A recent report showed that PCSK9 inhibition could inhibit tumor progression and improve survival in mice bearing colon cancer through anti-angiogenesis and anti-inflammation." (PMID 35806383, 2022). "Considering that both lactate and MIF regulate antitumor immunity and play a role in tumor microenvironment, we analyzed PCSK9 in regulation of TAMs polarization and found that PCSK9 was able to alter TAMs polarization in order to change the functions of TAMs in colon cancer." (PMID 36242053, 2022). "We therefore detected the changes in such protein expressions in colon cancer cells (i.e., knockdown of PCSK9 expression significantly upregulated level of E-cadherin protein), but downregulated expressions of N-cadherin, MMP9, and Snail 1 proteins in HCT116 and HT-29 cells." (PMID 36242053, 2022). "This study could offer novel mechanistic insights into the role of PCSK9 in colon cancer development and progression." (PMID 36242053, 2022). "Then, we explored PCSK9 regulation of the levels of protein lactylation by performed Western blot analysis using an anti-L-Lactyl lysine antibody and detected the levels of lactate in the cell supernatant of colon cancer cells by Lactate Assay Kit." (PMID 36242053, 2022). "We utilized the proteomic analysis to demonstrate that the reduction of PCSK9 expression in colon cancer cells induced differentially expressed proteins that were mainly enriched in cellular and metabolic processes, while level of MIF expression had a significant trend for decline." (PMID 36242053, 2022). "The data from our current study revealed that the influence of PCSK9 protein on different cellular processes in colon cancer and targeting of PCSK9 could be a novel approach to control of colon cancer in future clinical practice." (PMID 36242053, 2022). "According to these results, we performed Western blot to confirm expression of MIF proteins after knockdown of PCSK9 in HCT116 and HT-29 cells and found that PCSK9 knockdown in colon cancer cells significantly decreased MIF expression, consistent with the results of our proteomic analysis." (PMID 36242053, 2022). "Collectly, knockdown of PCSK9 expression could attenuate colon cancer cell lung metastasis in vivo." (PMID 36242053, 2022). "However, PCSK9 overexpression showed the inverse effects on colon cancer cells." (PMID 36242053, 2022). "Thus, we speculate that PCSK9 could be involved in regulation of the intracellular lactate metabolism in colon cancer cells." (PMID 36242053, 2022). "Targeting PCSK9 expression or activity could be used to effectively control colon cancer." (PMID 36242053, 2022). "PCSK9 blocking agents, especially when combined with statins, inhibit the neoplastic growth of APC/KRAS mutant colon cancer xenograft models by suppressing the KRAS/MEK/ERK pathway." (PMID 36900189, 2023). "For example, PCSK9 can effectively control colon cancer by regulating tumor cell EMT and the PI3K / AKT signaling pathway, promoting M2 polarization phenotype in macrophages through mediating MIF and lactate levels, and targeting PCSK9 expression." (PMID 39010066, 2024). "PCSK9 is highly expressed in colon cancer tissue, inducing the EMT process of colon cancer cells and activating the PI3K / AKT signaling, while suppressing PCSK9 expression promotes M1 macrophage polarization by reducing lactate, protein Kla, and macrophage migration inhibitory factor." (PMID 39010066, 2024). "Besides, PCSK9 directly or indirectly activated Snail 1 and subsequently to downregulate E-cadherin (but upregulate N-cadherin and MMP9) and then induce the colon cancer cell EMT process." (PMID 36242053, 2022). "PCSK9 directly or indirectly upregulated Snail 1 and in turn to downregulate E-cadherin expression, but upregulate N-cadherin and MMP9 levels and thereafter, to induce colon cancer cell epithelial-mesenchymal transition (EMT) process and activated PI3K/AKT signaling." (PMID 36242053, 2022).
colon cancer (continued). "However, PCSK9 knockout substantially suppressed tumor cell growth in mice depending on cytotoxic T cells and the inhibitory effects of PCSK9 was independent of its hypolipidemic pathway, which thus promoted us to further explore the role of PCSK9 in colon cancer." (PMID 36242053, 2022). "Moreover, knockdown of PCSK9 expression reduced colon cancer cell EMT and the activation of the PI3K/AKT signaling, while our proteomic analysis showed that the reduction of PCSK9 expression affected colon cancer cell metabolism as well as immune reactions to induce M1 macrophage polarization." (PMID 36242053, 2022).